MICU1 (mitochondrial calcium uptake 1)
Diseases named in the same sentence as MICU1 in open-access papers (continued):
Sharing a sentence is not in itself a finding about the gene and the disease.
tumor (22 papers, 2015 to 2025). "High MiCU1/2 expression correlates with increased infiltration of M2-type tumor-associated macrophages (TAMs), which promote tumor progression, angiogenesis, and immune evasion via immunosuppressive cytokines like IL-10 and TGF-β." (PMID 40867511, 2025). "More importantly, gain or loss function assays suggested that targeting MICU1 could compensate EZH2's effect on regulating tumor cell apoptosis." (PMID 26378043, 2015). "In OC, MICU1 enhances lactate production, promotes tumor growth, induces cisplatin resistance, and decreases patient survival." (PMID 40093000, 2025). "In conclusion, our findings demonstrate that MiCU1/2 is significantly downregulated in BRCA tissues, yet exhibits high diagnostic and prognostic value for BRCA, while also being intricately linked to tumor immune regulatory mechanisms." (PMID 38911376, 2024). "Through functional enrichment analysis, we highlighted the involvement of MiCU1/2 in immune responses, allowing for a deeper understanding of their roles in shaping the tumor microenvironment and interactions with different immune cell types." (PMID 38911376, 2024). "Tumor progression and immunomodulation are closely intertwined, suggesting a potential role for MiCU1/2 in BRCA pathogenesis through the immune microenvironment." (PMID 38911376, 2024). "We observed that MiCU1/2 positively regulates TAM-mediated tumor invasion, indicating a possible positive feedback loop between them." (PMID 38911376, 2024). "Although the localization of kinases without canonical mitochondrial targeting sequences remains controversial, this phosphorylation of MICU1 was shown to alter the [Ca2+]m accumulation, leading to ROS production and tumor progression." (PMID 32059571, 2020). "Among 126 tumour tissues, almost three-quarters (n=92, 73%) of samples had a moderate to high expression of MICU1 with a 95% Clopper-Pears on exact confidence interval (64%, 81%)." (PMID 28530221, 2017). "All of this data convincingly demonstrate that MICU1 is a key player for tumour growth and therapy resistance and targeting MICU1 sensitizes OvCa cells to cisplatin both in vitro and in vivo." (PMID 28530221, 2017). "The unavailability of any specific pharmacological inhibitor for MICU1 posits a challenge to establish roles of MICU1 in chemosensitization and tumour growth in vivo." (PMID 28530221, 2017). "To further validate the mechanisms of MICU1 induced glycolysis in tumour growth and therapy resistance in patients, we determined expression of pPDH(ser293) and MICU1 in chemoresistant patient TMA using immunohistochemistry." (PMID 28530221, 2017). "However, we observed that TCGA-COAD tumor samples with a “high” MICU1 status show higher expression of genes associated with the assembly of complexes I and IV of the mitochondrial respiratory chain compared with tumor samples with a “low” MICU1 status." (PMID 39466877, 2024). "Notably, macrophages exhibit substantial enrichment and infiltration within tumor tissues exhibiting high MiCU1/2 expression levels." (PMID 38911376, 2024). "The utilization of spatial transcriptome analysis revealed heightened expression of MiCU1/2 in tumors and its relevance in surrounding immune cells, shedding light on the intricate interplay between mitochondrial calcium handling and the tumor immune microenvironment (TIME)." (PMID 38911376, 2024). "Current evidence suggests that MiCU1/2 plays a crucial role in tumor formation and may contribute to tumor progression." (PMID 38911376, 2024). "Notably, our immunological assessment revealed a positive correlation between MiCU1/2 expression and increased macrophage infiltration, suggesting a potential role for MiCU1/2 in regulating macrophages within the tumor microenvironment." (PMID 38911376, 2024). "MCUR1 and MICU1 also influenced patients' prognosis and tumor occurrence and progression." (PMID 37056383, 2023).
tumor (continued). "However, very limited studies have detailed the regulatory mechanisms of MICU1, especially the participation of miRNAs in MICU1-regulated tumor progression." (PMID 35132320, 2022). "MiR-195 regulated tumor growth and MICU1 expression in ovarian." (PMID 34302635, 2021). "MICU1 knockdown was shown to inhibit tumor growth and increased cisplatin efficacy." (PMID 32059571, 2020). "Instead, post-translational modification of MICU1, namely its phosphorylation by a mitochondrial pool of Akt kinase was shown to increase the basal mitochondrial Ca2+ level, reactive oxygen species (ROS) production and tumor progression." (PMID 31159324, 2019). "Thus, MICU1 silencing increases survival in animals bearing OvCa tumours suggesting targeting MICU1 in OvCa could be a strategy to prolong survival in patients." (PMID 28530221, 2017). "Thus, MICU1 may be exploited as an important therapeutic target to normalize deranged metabolism to inhibit tumour growth and overcome therapy resistance." (PMID 28530221, 2017). "Using western blotting, we compared the protein expression of MCU, MICU1, and MICU2 in a non-tumor colorectal epithelial cell line, NCM356, and in 5 CRC cell lines (HT29, DLD1, SW480, HCT116, and SW620) with different mutation and aggressiveness profiles." (PMID 39466877, 2024). "There are several examples in the literature that demonstrate that tumor cells also adapt to prevent these deleterious surges in [Ca2+]m by regulating the MCU gatekeepers, MICU1, and MICU2." (PMID 32059571, 2020). "It has been reported that the promoters of other members can be recognized by CREB, and once bound to the promoter, the tumor highly expresses MCU, MICU1, and MICU2." (PMID 33114428, 2020). "This clinical analysis supports the concept that MICU1, by restricting Ca2+ entry into the mitochondria and thereby attenuating PDP activity, drives PDK-dependent phosphorylation of PDH in these tumours and thereby promotes aerobic glycolysis." (PMID 28530221, 2017). "To further support a role of MICU1 in promoting glycolysis in vivo, we determined the effect of MICU1 silencing on the expression and enzymatic activity of PDH in tumour tissue samples." (PMID 28530221, 2017). "Expression of MCU and its modulatory protein MICU1 are similar in normal and tumor cells at the mRNA level, being mRNA for MCU much more abundant than for MICU1." (PMID 28903423, 2017). "This suggests that MiCU1/2 may contribute to the immunosuppressive effects within the tumor microenvironment by promoting TAM activity, thereby facilitating tumor immune evasion." (PMID 38911376, 2024). "This study includes tumor specimens and adjacent normal liver tissue from 354 patients with confirmed HCC as study subjects and concluded that HCC patients with low MICU1 and high MCU/MICU2 expression exhibited poor survival rates, overall survival rates and disease-free survival rates." (PMID 35743109, 2022). "Interestingly, even in the presence of activated CREB, there is an increase in the levels of MCU, MICU1, and MICU2 that significantly enhances tumor growth." (PMID 33114428, 2020). "A fourth study correlated mRNA levels of MCU and related proteins (MCUb, MICU1–3, and EMRE) from the TCGA breast cancer dataset with clinical stages demonstrating that MCU expression increases with tumor size and lymph node infiltration, while MCUb expression decreases." (PMID 28740830, 2017). "The dot plot further delineates the levels of MiCU1/2 in non-tumor and tumor regions." (PMID 38911376, 2024). "Based on previous work demonstrating a role for FOXD1 in controlling expression of MICU1, which regulates calcium flux in the mitochondrion, we hypothesized that reduced proliferative capacity of FOXD1 null tumor cells may be due to reduced energy production capacity." (PMID 33761914, 2021).
tumor (continued). "Additionally, our study identified a positive correlation between MiCU1/2 levels and macrophage infiltration using the CIBERSORT algorithm, highlighting the potential impact of mitochondrial calcium regulation on immune infiltration dynamics within the tumor microenvironment." (PMID 38911376, 2024). "Thus, the MICU2/MICU1 ratio is positively correlated to the aggressiveness of a CRC tumor, suggesting that the stoichiometry of the regulatory units of MCU complex may be critical for the tumor development." (PMID 39466877, 2024). "The tumor cell lines showed significantly higher expression of MCU and MICU1 than the non-tumor cell line." (PMID 39466877, 2024).
myopathy (8 papers, 2020 to 2025). A disease of the muscle in which the muscle fibers do not function properly. "The panel also incidentally detected two MICU1 variants in the patient’s father, suggesting a diagnosis of autosomal recessive MICU1-associated myopathy with extrapyramidal signs." (PMID 35937981, 2022). "Myopathy with extrapyramidal signs (OMIM #615673) is a rare autosomal recessive disease due to a pathogenic variant in the MICU1 gene with a frequency lower than 1/1000000." (PMID 36425804, 2022). "Individuals carrying MICU1 mutations present with proximal myopathy, axonal peripheral neuropathy, varied involuntary movement and severe learning difficulties (myopathy with extrapyramidal signs, MPXPS #615673)." (PMID 36475414, 2022). "Mutations in MICU1 gene causes a very rare neuromuscular disease, myopathy with extrapyramidal signs (MPXPS), due to primary alterations in mitochondrial calcium signaling which demonstrates the key role of mitochondrial Ca2+ uptake." (PMID 33969448, 2021). "Myopathy with extrapyramidal signs (OMIM #615673) is a rare autosomal recessive mitochondrial disorder caused by mutations in MICU1 gene that typically causes muscle weakness with normal respiratory chain." (PMID 32293312, 2020). "Biallelic pathogenic variants in one nuclear‐encoded protein, mitochondrial calcium uptake 1 (MICU1) have recently been described to cause myopathy with extrapyramidal signs (MPXPS)." (PMID 32395406, 2020). "Myopathy with extrapyramidal signs (MPXPS) is an autosomal recessive mitochondrial disorder which is caused by mutation in mitochondrial calcium uptake 1 (MICU1) gene located on chromosome 10q22.1." (PMID 32293312, 2020). "Although MICU1-related myopathy with extrapyramidal signs (MPXPS) has been reported globally, its genotypic and phenotypic spectrum in Chinese populations remains poorly characterized." (PMID 41018190, 2025). "We suspect that this unusual phenotype of the proband with MICU1-related myopathy could be explained by the presence of the truncated but partly functional protein." (PMID 36425804, 2022). "Also, we present a case with the unusual presentation of MICU1-related myopathy due to homozygous ΔEx2 of the MICU1 gene." (PMID 36425804, 2022). "We believe that this case could expand the spectrum of clinical phenotypes for MICU1-related myopathy." (PMID 36425804, 2022). "Interestingly, mutations in MICU2 manifest as acute encephalopathy and associated cognitive impairment, but myopathy is absent – though these mutations are less frequently observed than those in MICU1." (PMID 36475414, 2022).
cardiovascular disease (4 papers, 2018 to 2025). "A previous study has reported that MICU1 protein expression is decreased in ECs from patients with cardiovascular diseases, accompanied by increased [Ca2+]m accumulation, mROS production, and halted EC migration." (PMID 40166941, 2025). "In sum, this study highlights MICU1 as a promising target for therapeutic intervention in cardiovascular diseases characterized by calcium overload and mitochondrial dysfunction." (PMID 40166941, 2025). "Finally, to explore the role of MICU1 in cardiovascular diseases in humans, we utilized Mendelian randomization (MR) studies." (PMID 40166941, 2025). "Clinical relevance of MICU1 expression to cardiovascular diseases in patients." (PMID 40166941, 2025). "To validate the correlation between MICU1 expression and cardiovascular disease, we collected atherosclerotic coronary arteries from patients with CAD and determined MICU1 levels in the plaque region." (PMID 40166941, 2025).
extrapyramidal movement disorder (4 papers, 2014 to 2020). "On the other hand, human mutations of MICU1 are associated with proximal myopathy, learning difficulties and a progressive extrapyramidal movement disorder and which are thought to arise from defective mitochondrial Ca2+ signaling." (PMID 25004162, 2014).
infection (2 papers, 2022). The state of being infected such as from the introduction of a foreign agent such as serum, vaccine, antigenic substance or organism. "Mcu, Micu1, and Vdac1 were all significantly downregulated for both shRNAs 7 days after infection, on DIV 10, suggesting that their altered expression was due to a homeostatic mechanism rather than an off-target effect of either shRNA." (PMID 34942149, 2022). "In conclusion, we have demonstrated that MICU1-dependent mCa2+ uptake plays an essential role in regulating AT2 cell differentiation into AT1 cells during steady-state tissue maintenance and alveolar epithelial regeneration after SpT4 infection–induced lung injury." (PMID 35050901, 2022).
neurodegenerative disease (2 papers, 2021 to 2025). A disorder of the central nervous system characterized by gradual and progressive loss of neural tissue and neurologic function. "This additional MICU1 checkpoint is of fundamental importance to guarantee cell survival of cells sensitive to Mn2+ such as neurons, thus setting MICU1 as a crucial safeguard against cellular toxicity due to manganese in neurodegenerative diseases." (PMID 34071006, 2021). "Our findings on the interaction between SIRT1 and MICU1 raise the question of whether SIRT1 exerts its protective effects in various neurodegenerative diseases through this pathway." (PMID 40003583, 2025). "Additionally, MCU and MICU1 expression levels are negatively correlated with age, potentially explaining the increased incidence of neurodegenerative diseases with aging." (PMID 40003583, 2025).
neuromuscular disease (2 papers, 2020 to 2021). "In addition, in a mouse model of neuromuscular disease caused by MICU1 deficiency, decreased EMRE expression over time correlated with improved health." (PMID 32769116, 2020).
mitochondrial disease (1 paper, 2019). "In addition, human patients with loss of function mutations in MICU1 display a clinical phenotype with multiple defects that recapitulates some clinical features of mitochondrial diseases." (PMID 31737163, 2019).
muscular disorder (1 paper, 2017). "Loss of function mutations of the protein MICU1, a regulator of mitochondrial Ca2 + uptake, cause a neuronal and muscular disorder characterised by impaired cognition, muscle weakness and an extrapyramidal motor disorder." (PMID 28132899, 2017).
MICU1 also shares sentences with these, for which no sentence is quoted: myocardial ischemia (2 papers); prostate carcinoma (2); Acute encephalopathy (1); Alzheimer disease (1); amyloid (1); angina pectoris (1); Arachnodactyly (1); breast tumors (1); Cerebral ischemia (1); cervical cancer (1); chronic renal failure (1); Diplopia (1); gastric cancer (1); genetic diseases (1); Huntington disease (1); Hyperglycemia (1); learning disability (1); lipid metabolism disorders (1); lobular carcinoma (1); lung carcinoma (1); lung injury (1); migraine with aura (1); muscle disorders (1); muscular dystrophy (1); progressive muscular dystrophy (1); renal cell carcinoma (1); Strabismus (1); triple-negative breast carcinoma (1); type I diabetic (1).